EEFSEC (eukaryotic elongation factor, selenocysteine-tRNA specific)
Description:
Translation factor required for the incorporation of the rare amino acid selenocysteine encoded by UGA codons. Replaces the eRF1-eRF3-GTP ternary complex for the insertion of selenocysteine directed by the UGA codon. Insertion of selenocysteine at UGA codons is mediated by SECISBP2 and EEFSEC: SECISBP2 (1) specifically binds the SECIS sequence once the 80S ribosome encounters an in-frame UGA codon and (2) contacts the RPS27A/eS31 of the 40S ribosome before ribosome stalling. (3) GTP-bound EEFSEC then delivers selenocysteinyl-tRNA(Sec) to the 80S ribosome and adopts a preaccommodated state conformation. (4) After GTP hydrolysis, EEFSEC dissociates from the assembly, selenocysteinyl-tRNA(Sec) accommodates, and peptide bond synthesis and selenoprotein elongation occur.
Synonyms: SELB; EFSEC; NEDPSB
Tractability: Small molecule: a structure with a bound ligand is known. PROTAC: ubiquitination databases record sites on it; its protein half-life has been measured.
Gene: Protein-coding gene on chromosome 3 (128,153,433 to 128,409,356, forward strand). Ensembl gene ENSG00000132394.
Subcellular location: Cytoplasm; Nucleus
Subcellular location (Human Protein Atlas): Nuclear bodies; Nucleoplasm; Cytosol
Pathways (Reactome):
Metabolism: Selenocysteine synthesis
Gene Ontology:
Molecular function: GTPase activity; translation elongation factor activity; GTP binding; ribonucleoprotein complex binding; selenocysteine insertion sequence binding; tRNA binding
Biological process: selenocysteine incorporation; selenium compound metabolic process
Cellular component: cytoplasm; cytosol; nucleus; ribonucleoprotein complex
Genetic constraint (gnomAD): Loss-of-function variants: 43 observed, 41.24 expected, observed/expected ratio (o/e) 1.04, 90% interval 0.82 to 1.35. The upper end of that interval is the gene's LOEUF score, 1.35, which puts it in group 5 of 6, group 1 being the genes least tolerant of losing a copy. Missense variants: 731 observed, 775.21 expected, observed/expected ratio (o/e) 0.94, 90% interval 0.89 to 1. Synonymous variants: 348 observed, 325.09 expected, observed/expected ratio (o/e) 1.07, 90% interval 0.98 to 1.17.
Homologues: Orthologues: chimpanzee EEFSEC (99% identical), macaque EEFSEC (98% identical), dog EEFSEC (92% identical), rabbit EEFSEC (90% identical), pig EEFSEC (89% identical), rat Eefsec (88% identical), mouse Eefsec (88% identical), guinea pig EEFSEC (87% identical), tropical clawed frog eefsec (70% identical), zebrafish eefsec (63% identical), Drosophila melanogaster eEFSec (41% identical), Caenorhabditis elegans efsc-1 (29% identical). Paralogues in human: HBS1L (19% identical), EFL1 (17% identical), EEF1A1 (15% identical), GFM2 (15% identical), EEF1A2 (15% identical), TUFM (15% identical), EEF2 (15% identical), GFM1 (14% identical), GUF1 (13% identical), EIF2S3B (13% identical), EFTUD2 (13% identical), EIF2S3 (13% identical), and 6 more.
Diseases named in the same sentence as EEFSEC in open-access papers:
EEFSEC is named in the same sentence as 13 diseases in open-access papers, as found by Europe PMC text mining. Sharing a sentence is not in itself a finding about the gene and the disease. The quoted sentences say what the papers report.
developmental delay (2 papers, 2025). "EEFSEC deficiency, an autosomal recessive disorder, manifests with global developmental delay, progressive spasticity, ataxia, and seizures." (PMID 39753114, 2025). "This study investigates a 4-year-old girl with global developmental delay and cerebellar atrophy, revealing compound heterozygous variants in the EEFSEC gene (p.V488Dfs*113 and p.R443P) through extensive genetic analysis and whole exome sequencing." (PMID 40652205, 2025). "Bi-allelic variants in EEFSEC, essential for selenoprotein biosynthesis, cause a novel selenopathy with early-onset neurodegeneration characterized by developmental delay, spasticity, seizures, and cerebellar atrophy." (PMID 39753114, 2025).
asthma (1 paper, 2025). "Several loci previously associated with childhood asthma (e.g., 15q22.33, 16p12.1, and 3q21.3 near genes SMAD3, IL4R, EEFSEC, respectively) were also linked here with a more generally selected asthma." (PMID 41213931, 2025).
breast carcinoma (1 paper, 2020). "The treatment with CyA restored the abundance of 3 proteins at 1% oxygen to a level similar to that in cells grown at 19% oxygen, selenocysteine-specific elongation factor (EEFSEC), Bardet-Biedl syndrome 12 protein (BBS12) and breast cancer anti-estrogen resistance protein 3 (BCAR3)." (PMID 32183695, 2020).
Cerebellar atrophy (1 paper, 2025). Cerebellar atrophy is defined as a cerebellum with initially normal structures, in a posterior fossa with normal size, which displays enlarged fissures (interfolial spaces) in comparison to the foliae secondary to loss of tissue. "This case link a human disease directly to variants in the EEFSEC gene, emphasizing its vital role in cerebellar atrophy and the broader implications for genetic disorders related to defects in selenoprotein synthesis." (PMID 40652205, 2025). "In summary, we report a child with progressive cerebellar atrophy caused by variants in the EEFSEC gene and confirm its role in the pathogenesis of the disease in the reported case." (PMID 40652205, 2025). "Progressive cerebellar atrophy due to a compound heterozygous pathogenic variant in the EEFSEC gene expands the genetic subtypes of this disease." (PMID 40652205, 2025). "Variants in genes involved in selenoprotein translation, such as SEPSECS and EEFSEC, can lead to progressive cerebellar atrophy, demonstrating the vital role of selenoproteins in maintaining cerebellar function." (PMID 40652205, 2025).
chronic obstructive pulmonary disease (1 paper, 2025). A chronic and progressive lung disorder characterized by the loss of elasticity of the bronchial tree and the air sacs, destruction of the air sacs wall, thickening of the bronchial wall, and mucous accumulation in the bronchial tree. "Moreover, certain genetic polymorphisms in the EEFSEC gene have been identified as potential risk factors for various diseases, including chronic obstructive pulmonary disease, preterm birth, and periodontitis." (PMID 40652205, 2025).
endometrial cancer (1 paper, 2021). Primary or metastatic malignant neoplasm involving the endometrium (mucous membrane that lines the endometrial cavity). "Two candidate endometrial cancer susceptibility genes (CYP19A1 and EEFSEC) were prioritized using both S-MultiXcan-colocalization and MR-JTI approaches." (PMID 34675350, 2021). "The associations of CYP19A1, SKAP1, HEY2, EEFSEC, and EVI2A were supported by colocalization of eQTL and GWAS signals in at least one of the relevant tissues; thus, these five genes were prioritized as candidate endometrial cancer susceptibility genes." (PMID 34675350, 2021). "Two of the candidate susceptibility genes (AC021755.3 and EEFSEC) have not been previously reported and EEFSEC is located outside established endometrial cancer GWAS risk loci." (PMID 34675350, 2021). "To prioritise the genes identified by JTI, we performed a Mendelian randomization (MR) causal inference analysis in the respective tissues using MR-JTI, providing five candidate endometrial cancer susceptibility genes: CYP19A1, SNX11, AC021755.3, EEFSEC, and EIF2AK4." (PMID 34675350, 2021).
endometriosis (1 paper, 2023). The growth of functional endometrial tissue in anatomic sites outside the uterine body. "Expression of four of the genes (EEFSEC, GDAP1, ADK, and SKAP1) was also significantly associated with endometriosis risk when SMR analyses were conducted using the eQTL and GWAS summary statistics." (PMID 37587191, 2023). "New endometriosis target genes detected include EEFSEC (eukaryotic elongation factor, selenocysteine-TRNA specific) on chromosome 3q21.3, SRD5A3 (steroid 5 α-reductase 3) on chromosome 4q12, ADK (adenosine kinase) on chromosome 10q22.2, and HOXC cluster on chromosome 12." (PMID 37587191, 2023).
hepatoma (1 paper, 2016). "In an effort to gain more insight into a function for eEFSec nuclear localization, we analyzed the subcellular localization of N-terminally FLAG-tagged mouse eEFSec that was stably transfected into a rat hepatoma cell line, McArdle 7777." (PMID 27802322, 2016). "We identified several novel sequences that are critical for both the activity and shuttling of eEFSec, and we demonstrate that disrupting eEFSec localization does not alter selenoprotein production in rat hepatoma cells." (PMID 27802322, 2016).
tumor (2 papers, 2022 to 2025). "EEFSEC is a member of the eukaryotic family of elongation factors, and its role in tumor cells has been rarely reported." (PMID 41247789, 2025).
EEFSEC also shares sentences with these, for which no sentence is quoted: Ataxia (1 paper); cancer (1); genetic disorders (1); periodontitis (1).